TNF (tumor necrosis factor)
Diseases named in the same sentence as TNF in open-access papers (continued):
Sharing a sentence is not in itself a finding about the gene and the disease.
cancer (continued). "Generally, XIST expression was positively related to about half of these markers in various cancers, such as CD2000, CD200R1, CD274, members of the tumor necrosis factor (TNF) ligand family, and so on." (PMID 36212008, 2022). "Blocking these molecules by ICIs allows eliminating local suppression and inducing cancer-cell killing by CD8 positive T cells producing interferon gamma (IFN-γ) and tumor necrosis factor α (TNF-α)." (PMID 36533080, 2022). "In the co-culture of activated CD8+ T cells and 4T1 cancer cells, TEM alone or in combination with anti-PD-L1 effectively increased the release of TNF-α from CD8+ T cells." (PMID 36077620, 2022). "CXCL10 and CXCL11 were predominantly synthesized and produced by monocytes, endothelial cells, fibroblasts, and cancer cells under the induction of IFN-γ and TNFα." (PMID 36003333, 2022). "Tumor necrosis factor (TNF) is a key regulator of innate immunity and plays a paradoxical and dual role in human cancers, promoting cancer survival or cell death depending on the cellular context." (PMID 35372081, 2022). "KEGG analysis discovered that these DEGs mainly participated in focal adhesion, proteoglycans in cancer, the PI3K-AKT signaling pathway, NF-kappa B and TNF signaling pathway." (PMID 35342418, 2022). "Both are closely related to cancer and immune signaling pathways, such as the chemokine signaling pathway, Jak-STAT signaling pathway, TNF signaling pathway." (PMID 35397536, 2022). "The most important enriched cancer-related signaling pathways by these genes were: the “PI3K-AKT signaling pathway, the “HIF-1 signaling pathway”, and the “TNF signaling pathway”." (PMID 35711939, 2022). "A proinflammatory cytokine, tumor necrosis factor (TNF) mediates phosphorylation and activation of NF‐κB which controls cell survival and proliferation of various cancer cells." (PMID 35274824, 2022). "Our previous studies demonstrated that in addition to their cytotoxic function, NK cells have a significant role in promoting differentiation of cancer stem cells (CSCs) by providing critical signals via secreted and membrane bound IFN-γ and TNF-α." (PMID 35203349, 2022). "To further confirm the effect of PARs on the production of TNF-α in macrophages and CXCL1 in cancer cells, we treated RAW 264.7 cells with a PAR1 or PAR2 inhibitor." (PMID 36552865, 2022). "have recently demonstrated that circular ubiquitin-specific protease-7 (circUSP7) in NSCLC TDEs inhibits the secretion of IFN-γ, TNF-α, granzyme-b, and perforin by CD8+T cells and promotes the formation of a cancer immunosuppressive microenvironment." (PMID 36727049, 2022). "Both tumor necrosis factor-α (TNF-α) and transforming growth factor-β (TGF-β) are critical cytokines in the cancer microenvironment." (PMID 36497431, 2022). "NF-κB can be activated by TNF-α, which leads to the expression of genes that code enhanced proinflammatory activity, thus linking TNF-α and NF-κB to inflammation and cancer." (PMID 35163356, 2022). "Soluble TNFR2 is an indicator in the serum of patients with cancer, and it also represents the level of active TNFR2 in the TNF-stimulated cell culture medium." (PMID 35494080, 2022). "In a study, BV6 causes the induction of apoptosis via IAP degradation and sensitization by producing death ligands, tumor necrosis factor-α (TNF-α), and TNF-related apoptosis-inducing ligands (TRAILs) in various human cancer cell lines." (PMID 36358282, 2022). "Together, our data indicate that HB-EGF, shed from cancer cells by ADAM17, amplifies TNF-α and CSF-1 signaling in nearby macrophages." (PMID 35998057, 2022).
cancer (continued). "TNF and TNFSF10 (TRAIL) secreted by M1-like and M2-like macrophages interact with their receptors expressed on cancer cells." (PMID 34793335, 2022). "This interaction induces the release of highly cytotoxic molecules from CD8+ T cells including perforin, granzyme, tumor necrosis factor (TNF) α and interferon (IFN) γ, which leads to the induction of cancer cell death." (PMID 35677057, 2022). "To study the genomic binding landscapes of p65 and E2F1 and their overlap in HeLa cancer cells, we re-analysed publicly available ChIP-seq data for p65 following TNFα stimulation, and E2F1 prior to TNFα stimulation." (PMID 36291831, 2022). "Proinflammatory cytokines such as TNF-α, IL-6, IL-1β, TGF-β, and IFN-γ modulate PD-L1 expression in both cancer and stromal cells." (PMID 35326493, 2022). "Administration of DOX increases HMGB1 expression and induces TNF- secretion via TLR4, whereas HMGB1 released from necrotic cancer cells treated with necrosis inducers increases regrowth and metastasis of residual cancer cells through RAGE activation." (PMID 35340325, 2022). "Many studies demonstrate that Th1 cells have a key role in combating cancers by secreting IFN-γ, IL-2, and TNF-α." (PMID 35433680, 2022). "Inflammation with deregulated cytokines IL-1, TNF, IL-6, and IL-23/IL17 is reported as a crucial factor for the development of cancer and is controlled and modified with miRNAs." (PMID 36555323, 2022). "Ads that were engineered to express immune-stimulatory cytokines and other immune-modulatory molecules such as TNF-α, IL-2, BiTE, CD40L, 4-1BBL, GM-CSF, and IFN have shown promising outcome in treatment of cancer." (PMID 35756634, 2022). "Crosslinking between CSCs and two pathways- TNF-α/ NF-κB signaling and IL-6/STAT3- regulates the differentiation of many immune cells in TME, promoting immunosurveillance and cancer progression." (PMID 36207500, 2022). "In addition, while it is believed that HPV infection alone may be insufficient for the oncogenic transformation of normal epithelial cells recent studies suggest that chronic exposure of TNF to HPV-infected oral keratinocyte cell lines increases cancer stem cell-like populations and stemness." (PMID 35844493, 2022). "These pro-inflammatory cytokines, such as IFN-γ and tumor necrosis factor (TNF), and chemokines, such as CXCL10, are critical for modulating adaptive immune response to inhibit cancer cells in the TME." (PMID 35455671, 2022). "The anti-viral or anti-cancer activity of CD8+ T cells is mediated by a polyfunctional Type1 cytokine response (e.g., IL-2, IFNγ, and TNFα)." (PMID 36619639, 2022). "TNF‐α promotes stemness by inducing the EMT pathways, and it was well demonstrated in renal and cholangiocarcinoma cancers." (PMID 36550571, 2022). "In summation, these recent findings prompt testing therapeutic strategies combining anti-PD1 checkpoint blockade with Fn14 activation to sensitize cancer cells for TNF killing and/or TNFR2 activation to enhance CD8+ T-cell activation and TNF release." (PMID 35681583, 2022). "Correlation analysis of FDX1 with checkpoint gene expression found a high correlation (p < 0.05) with tumor necrosis factor (TNF)–related immune genes (TNFRSF14, 15, 25) and CTLA4, PDCD1, CD274, NRP1, and VTCN1 in some kinds of cancers." (PMID 36061184, 2022). "We found that Blimp-1 is localized in the nuclei of both cancer cell lines and is still kept in the nuclei after PMA, TNF-α or UVB stimulation." (PMID 35185556, 2022). "TNFSF10, the superfamily member 10 of tumor necrosis factor (TNF), acts in an antitumor capacity by inducing cancer cell apoptosis while interacting with the corresponding receptor." (PMID 35755810, 2022).
cancer (continued). "Several lines of investigations established that stromal expression of soluble factors including HGF, TNF-α and WNT16B in the TME can promote cancer resistance to chemotherapy, radiation and targeted agents." (PMID 36202915, 2022). "The improvement in the immunity observed in blood samples of the patients doing exercise at home revealed a significant reduction in TNF-α, CRP, IL-8, and an increase in NK cell levels which ultimately give advantages to the cancer patients." (PMID 35935260, 2022). "Enriched functional categories included transcription misregulation in cancer, cell cycle, ECM–receptor interaction, focal adhesion, PI3K-AKT/TNF/IL-17/JAK-STAT signaling pathways, and cytokine–cytokine receptor interaction." (PMID 35737114, 2022). "The significantly (P < 0.001) enriched pathways were related to cytokine-cytokine receptor interaction, PI3K-AKT, TNF signaling, proteoglycans in cancer, MAPK, JAK-STAT, pathways in cancer, apoptosis, NF-κB and transcriptional misregulation in cancers." (PMID 34991623, 2022). "The genes were significantly enriched in 7 pathways, namely, pathways in cancer, cAMP signaling pathway, metabolic pathways, PPAR signaling pathway, TNF signaling pathway, PI3K-Akt signaling pathway, and AGE-RAGE signaling pathway in diabetic complications." (PMID 36310619, 2022). "Macrophages are activated by cancer cell-derived TNC and subsequently stimulate lung ECs by secreting NO and TNF to invoke vascular niche formation." (PMID 35469015, 2022). "TNF-α and TGF-β are critical cytokines in the metastatic microenvironment, affecting cancer growth and metastasis." (PMID 36497431, 2022). "The senescence-inducing effect was replicable in other types of cancer cells (e.g., melanoma, breast cancer) receiving combined treatment with recombinant IFN-γ and TNF." (PMID 36611926, 2022). "It is noteworthy that nuclear programmed death ligand 1 (nPD-L1) can upregulate GSDMC, whereas TNF-α-activated caspase-8 can cleave GSDMC, which will switch apoptosis to pyroptosis in cancer cells." (PMID 35962439, 2022). "TNF-α is ubiquitously expressed in many types of cancer cells, including OSCC cells, and it was shown that TNF-α alone induced osteoclastogenic activity." (PMID 36614130, 2022). "Pathway analysis showed multiple pathways upregulated related to cancer, mechanotransduction, ECM sensing, cellular senescence, EMT, TNF-α, and IL-17 signaling." (PMID 36163190, 2022). "Peiminine downregulates the expression of inflammatory cytokines in cancer cells, decreasing the levels of COX-2, TNF-α, IL-1β, as well as suppressing NF-κB signaling." (PMID 36582529, 2022). "Blick and colleagues discovered in 1987 a decrease in haemoglobin synthesis in cancer patients treated with TNF-α, and an in vitro study revealed that TNF-α inhibited the formation of burst-forming unit-erythrocyte (BFU-E) cells." (PMID 36612220, 2022). "TME cells secrete a variety of pro-inflammatory cytokines that interfere with anti-cancer immune response (VEGF), interleukins (IL-6, IL-12), epidermal growth factor (EGF), as well as tumor necrosis factor-alpha (TNF-a) and indoleamine-2,3-dioxygenase (IDO)." (PMID 35743107, 2022). "Cancer triggers systemic inflammation with a corresponding increase in pro-inflammatory cytokines such as interleukin 6 (IL6) and tumor necrosis factor α (TNFα)." (PMID 35327399, 2022). "• Mediate metastatic cancer cells dormancy through cell cycle arrest by IFN-γ and TNF-α.• A significant enrichment of convergent TCR clusters.• Enriched with activated HLA-DR+ and ICOS+ and proliferating KI67+ cells.• A high proportion of HPV-specific T cells." (PMID 36451828, 2022). "Against all tested cancer cell lines, the BAFF CAR-T cells released significantly higher levels of the pro-inflammatory cytokines TNF-α and IFN-γ, lytic enzymes granzymes A and B and perforin, soluble Fas ligand (sFasL), and granulysin." (PMID 35017485, 2022).
cancer (continued). "KEGG analysis revealed that both inhibitor combinations were involved in immune regulation, signal transduction (especially PI3K/AKT, TNF, and JAK-STAT signaling pathways), metabolic activity, and cancer pathways (especially proteoglycans in cancer)." (PMID 36139627, 2022). "TNF-α production in dysplastic, primary, and metastatic ALPK1-depleted human oral (pre)cancer cells is reduced." (PMID 36139553, 2022). "Among them, the pathways of count number > 12 include cancer, PI3K-Akt, MAPK, TNF, FOXO, thyroid hormone signalling pathway, and local adhesion pathways." (PMID 36102631, 2022). "Overall, all of these studies suggested that propolis and its constituents inhibit cell proliferation, survival, and cell cycle by altering various signaling pathways (PI3K/Akt, MAPK, TNF-α/NF-κB, Wnt/β-catenin, and STAT-3/PLK-1) in several cancers." (PMID 35754701, 2022). "Based on our in vitro experiments that stimulate cancer cells, it appears that individual factors act in a cell-specific manner; in CMT cells, TNFα is the dominant factor, whereas in EA1 cells IL-1β is the most potent." (PMID 36686777, 2022). "M1-related TNFα and CD86 markers increased after inoculation with ferumoxytol plus cancer cells, whereas M2-related CD206 and interleukin (IL)-10 markers decreased." (PMID 36587223, 2022). "Cancer patients exhibit lower NK cell proliferation and demonstrate decreased production of IFN-γ and TNF-α." (PMID 35203349, 2022). "The significantly enriched pathways included hematopoietic cell lineage, TNF signaling pathway, RIG-I-like receptor signaling pathway, pathways in cancer, Lysosome, osteoclast differentiation, Th17 cell differentiation and so on." (PMID 35386709, 2022). "The levels of IL-6, IL-10, IL-17, transforming growth factor β1 (TGF-β1) and tumor necrosis factor α (TNF-α) in serum were measured to investigate the relationship between these indicators, cancer and treatment." (PMID 35889444, 2022). "An elevated level of TNF-α and IL6 has been found in the serum of cancer patients treated with gemcitabine." (PMID 34771621, 2021). "A total of 104 pathways were obtained by KEGG pathway analysis, including neuroactive ligand-receptor interaction, calcium signaling pathway, pathways in cancer, cGMP-PKG signaling pathway, and TNF signaling pathway." (PMID 34725557, 2021). "The most significantly enriched pathways were the TNF signalling pathway, prolactin signalling pathway, NF-κB signalling pathway, HTLV-1 infection, pathways in cancer, etc." (PMID 34259096, 2021). "Specifically, these pathways were mainly correlated with cancer, such as pathways in cancer, PI3K-AKT, MAPK, HIF-1, and TNF signaling pathway." (PMID 34938346, 2021). "Many types of cancer cells, including NSCLC cells, are relatively resistant to TNF-α-mediated cytotoxicity." (PMID 33633307, 2021). "Therapies such as interferon gamma (IFN-γ), IL-2, and tumor necrosis factor (TNF-α), have been approved for cancer treatment." (PMID 34541363, 2021). "For example, the antiviral pathways induced by type I interferon (IFN) and tumor necrosis factor (TNF), two antiviral cytokines that can restrict MYXV replication in normal human or mouse cells, are frequently defective in many cancer cells (2, –, 5)." (PMID 33952639, 2021). "Further visualizing the important cancer-related pathways, we found that cluster 2 had more EMT, KRAS and TNF signaling pathways, which was consistent with the worse prognosis associated with this cluster." (PMID 33973529, 2021). "Activators of ERK5, including mitogen-activated protein kinase 5 (MEK5), tumor necrosis factor α (TNF-α), and transforming growth factor-β (TGF-β), are known to induce EMT and metastases in breast, lung, colorectal, and other cancers." (PMID 33572742, 2021).
cancer (continued). "The identified pathways associated with the HlyA effect combine different target molecules including Ca2+- or TNF-dependent MLCK activation, AKT activation and PTEN inhibition as well as cancer signaling." (PMID 34437391, 2021). "In cervical cancer and ovarian cancer, TNF-α and TGF-β induce EMT and cancer stem cell-like properties through the NF-κB/Twist axis." (PMID 35069596, 2021). "In this review, it is evident that there are many potential applications to manipulate TNF-α pathways, specifically in its role in the TME for cancer therapy." (PMID 33986746, 2021). "When TH1 and TH2 cytokine levels in the serum and cancer tissues were compared, TH1 cytokines IL-2, TNF-α, IFN-γ, and IL-13 were significantly increased in patients compared to healthy controls." (PMID 34012451, 2021). "In a separate analysis, inflammatory cytokines, IL-1β, and TNF-α potently induce NR4A2 expression, which, in the presence of TGFβ, potentiates SMAD activation of fibrosis and cancer development." (PMID 33634114, 2021). "TNF-α treatment and chemotherapy also induce pyroptosis in GSDME-expressing cancer cells via activation of caspase-3." (PMID 33941231, 2021). "Cytokine release results showed that numerous inflammatory cytokines-chemokines related to cancer initiation and development, such as IL-8, IL-6, VEGF, MCP1, TNF-α were significantly increased in LIN28B-overexpressing MMNK-1 cells." (PMID 34837926, 2021). "Logistic regression analysis including the eight cytokines increased in cancer compared to control (GMCSF, IL-1β, IL-6, IL-8, Rantes/CCL5, MIP1α, TNFα, MCP1) was performed." (PMID 35048057, 2021). "This disturbs the equilibrium of the TNF-α/TNFR2 expression pattern, presumably putting cancer development in the third situation already described, i.e., the impairment of Teff function due to chronic exposure of both Tregs and Teffs to TNF-α." (PMID 34712661, 2021). "With 10 identifiers, we observed that these genes interacted with stemness genes such as SOX-2 and NANOG, genes important in cancer pathways such as STAT3, CTNNB1, EGFR, TNF, and CASP3, and immune genes such as IL2 and CD4." (PMID 34685742, 2021). "One of the characteristic hallmarks of cancer progression is hypoxia-induced cytokines such as vascular endothelial growth factor (VEGF), TNF-a, interleukins, etc." (PMID 34096454, 2021). "Studies have demonstrated that TNF-α inhibits TGF-β and ECM production, such as type I collagen and elastin in cancer cells and fibroblasts." (PMID 33986746, 2021). "To determine if persistent TNFα + IL-1β stimulation modifies invasion-related functions in TNBC cells, we analyzed the ability of the cancer cells to undergo epithelial-to-mesenchymal transition (EMT)." (PMID 34072893, 2021). "Furthermore, the commonly prescribed lipid-lowering atorvastatin had shown to diminish the PD-L1 induction by IFNγ alone or IFNγ/TNFα combination, implying that the use of atorvastatin might be helpful in developing therapeutic strategies to counter the immune evasion in cancers." (PMID 34445462, 2021). "TNF-α is a cytokine that is secreted during the inflammatory process accompanying RTH and during cancer development." (PMID 34150619, 2021). "TNFα is also overexpressed in oral squamous cell carcinoma (OSCC), promotes the sphere-forming abilities of its cells maintaining a cancer stem cell-like phenotype, and increases proliferation in leukemia stem cells." (PMID 33540543, 2021). "The platform was able to screen effects of TNF-α and TGF-β1 on cancer metastasis, displaying an improvement of the invasion and migratory potential of U87 cancer cells 48 h after applying TNF-α and TGF-β1." (PMID 33926127, 2021).